BDNF (brain derived neurotrophic factor)
Diseases named in the same sentence as BDNF in open-access papers (continued):
Sharing a sentence is not in itself a finding about the gene and the disease.
thrombosis (5 papers, 2019 to 2025). "Despite a focus on BDNF in CNS responses and affective outcomes, recent evidence implicates BDNF signalling in thrombosis and CAD." (PMID 37153459, 2023). "Some osmotic edema MYH6-Cre-BDNF–/– hearts also exhibited right atrial appendage thrombosis, left and right atrial thrombosis and/or left ventricular thrombosis." (PMID 36061561, 2022). "In addition to left atrial appendage thrombosis, some MYH6-Cre-BDNF–/– osmotic edema hearts also showed right atrial appendage thrombosis, left and right atrial thrombosis and left ventricular thrombosis." (PMID 36061561, 2022).
vitiligo (5 papers, 2022 to 2025). Generalized well circumscribed patches of leukoderma that are generally distributed over symmetric body locations and is due to autoimmune destruction of melanocytes. "After analyzing the laboratory data of the two groups, we were able to establish a significant relationship between the CRH-R1 rs242924 and BDNF rs11030094 polymorphisms and vitiligo." (PMID 35905107, 2022). "Our results indicated the association of both CRH-R1 rs242924 and BDNF rs11030094 polymorphisms with the risk of vitiligo occurrence, but more research is certainly needed to confirm these results." (PMID 35905107, 2022). "Our findings demonstrated the association between CRH-R1 rs242924 and BDNF rs11030094 polymorphisms and vitiligo." (PMID 35905107, 2022). "There was a significant relationship between the CRH-R1 rs242924 and BDNF rs11030094 polymorphisms and vitiligo." (PMID 35905107, 2022). "Serum brain-derived neurotrophic factor (BDNF) and serum vitamin D are decreased both in AA (N = 30) and vitiligo (N = 30), as compared with controls (N = 30)." (PMID 38673994, 2024). "At last, we explored a possible contribution of CRH-R1 and BDNF gene variations to the pathogenesis of vitiligo." (PMID 35905107, 2022). "The serum levels of BDNF were significantly lower in vitiligo patients than in healthy individuals, while the serum levels of CRH were markedly higher in cases than those in controls." (PMID 35508633, 2022). "Keeping in mind the contribution of neuropsychiatric abnormalities to vitiligo development, the same results of BDNF measurements in population with mental problems are expected." (PMID 35905107, 2022). "The serum levels of BDNF were significantly lower in vitiligo patients than in healthy individuals (Z = 4.002; P < 0.001), while the serum levels of CRH were markedly higher in cases than those in controls (Z = 3.764; P < 0.001)." (PMID 35508633, 2022). "Healthy controls in both GG-genotype and GA-genotype subgroups had significantly lower serum BDNF levels as compared with the vitiligo patients." (PMID 35905107, 2022). "The serum level of BDNF was significantly lower in vitiligo patients as compared with the healthy controls (2.60 (1.88–3.01) vs. 3.23 (2.52–4.33); P < 0.001)." (PMID 35508633, 2022). "This study was aimed at investigation of the serum levels of BDNF and CRH as well as their selected single nucleotide polymorphisms (SNPs) in vitiligo patients in comparison with the healthy controls." (PMID 35905107, 2022). "In this study, there were significantly lower BDNF levels in vitiligo patients than in controls." (PMID 35508633, 2022). "Moreover, serum levels of neurotransmitters differed significantly between vitiligo and control groups and were associated with the CRH-R1 rs242924 and BDNF rs11030094 SNPs." (PMID 35905107, 2022). "Also, the current study makes a significant contribution to the limited evidence of relationship between BDNF, vitiligo, and mental comorbidities." (PMID 35508633, 2022). "Furthermore, some authors hypothesized that reduced serum BDNF levels may be an etiologic factor for the development of vitiligo and may also be an indicator of future psychiatric comorbidity in this category of patients." (PMID 35905107, 2022). "In fact, psychiatric biomarkers such as brain-derived neurotrophic factor (BDNF) and corticotropin-releasing hormone (CRH) have been found to be down and upregulated respectively in vitiligo patients." (PMID 40303919, 2025). "Our recent study also demonstrated the decreased level of serum BDNF and increased level of serum CRH in vitiligo patients in comparison with the healthy controls." (PMID 35905107, 2022). "The aim of our study was to investigate the serum levels of BDNF and CRH, as well as their individual SNPs, in patients with vitiligo and healthy comparators." (PMID 35905107, 2022). "Thus, we aimed to investigate the serum levels of BDNF and CRH as well as their selected SNPs in vitiligo patients and healthy controls." (PMID 35905107, 2022).
vitiligo (continued). "The genes encrypting brain-derived neurotrophic factor (BDNF) and corticotropin releasing hormone (CRH) might be the conceivable contributors to the development of vitiligo." (PMID 35905107, 2022). "The area under curve (AUC) for serum BDNF showed no prognostic value of vitiligo (AUC = 0.333)." (PMID 35508633, 2022).
age-related macular degeneration (4 papers, 2020 to 2025). Age-related loss of vision in the central portion of the retina (macula), secondary to retinal degeneration. "According to the known physiologic mechanisms of BDNF, the impact of this protein has been studied in age-related macular degeneration (AMD)." (PMID 32509339, 2020).
Angelman syndrome (4 papers, 2013 to 2024). A neurogenetic disorder characterized by severe intellectual deficit and distinct facial dysmorphic features. "Brain-derived neurotrophic factor signaling is defective in Angelman syndrome and can be rescued by disruption of Arc/PSD95 binding." (PMID 23424281, 2013). "In Angelman syndrome, where BDNF signaling is impaired, CN2097 enhanced BDNF signaling to restore long-term potentiation and mitigate neurological deficits." (PMID 38743493, 2024).
Bardet-Biedl syndrome (4 papers, 2014 to 2025). A ciliopathy with multisystem involvement. "Here we report a role for the Bardet-Biedl Syndrome gene, BBS4, in regulation of BDNF signaling through the TRKB receptor in cultured human cells." (PMID 24867303, 2014).
binge eating disorder (4 papers, 2021 to 2024). Recurrent episodes of over-eating. "One comprehensive study on serum BDNF concentrations in a sample comprised of individuals with AN, BN and binge-eating disorder (BED) reported decreased BDNF levels in AN and BN, but not in BED." (PMID 33572701, 2021).
cannabis abuse (4 papers, 2013 to 2024). "This could have implications for the effects of cannabis abuse in humans in a subset of individuals with low BDNF signaling." (PMID 24155701, 2013). "We used BDNF heterozygous (HET) mice and treated them with CP from 6 to 9 weeks of age (adolescence/young adulthood) which represents a critical time window for detrimental effects of cannabis abuse." (PMID 24155701, 2013).
cardiomyopathy (4 papers, 2019 to 2025). A disease of the heart muscle or myocardium proper. "This study also identified the cardiac myocyte as a significant local source of BDNF, as cardiac myocyte-specific deletion of BDNF induced a similar cardiomyopathy phenotype." (PMID 31105581, 2019). "Indeed, hearts from mice deleted in TrkBT1 fail to exhibit enhanced contractile force in response to BDNF, and these mice develop an adult-onset cardiomyopathy, consistent with the observed expression of the TrkBT1 isoform in adult cardiac myocytes." (PMID 31105581, 2019).
chronic heart failure (4 papers, 2017 to 2023). "Similar neuromodulatory effects of BDNF have been observed in congestive heart failure, insulin secretion after chronic exercise, and carbachol-induced contraction of intestinal longitudinal smooth muscle." (PMID 29540150, 2018).
chronic pancreatitis (4 papers, 2012 to 2025). A chronic inflammatory process causing damage and fibrosis of the pancreatic parenchyma. "In humans, BDNF expression in the pancreas is upregulated and associated with pain in chronic pancreatitis." (PMID 22715356, 2012). "Serum from phenotyped individuals with CP from the PROspective Evaluation of Chronic Pancreatitis for EpidEmiologic and Translational StuDies (PROCEED) was assessed for BDNF levels using Meso Scale Discovery Immunoassay." (PMID 39674387, 2025). "We found no study in the literature about the association between BDNF expression in the blood and alcoholic pancreatitis or alcoholic liver disease, and only some studies have associated alterations in BDNF with non-alcoholic chronic pancreatitis and non-alcoholic hepatitis." (PMID 29108028, 2017). "In an independent cohort of individuals from the PROCEED study, we found that serum BDNF levels were indeed significantly upregulated in subjects with painful chronic pancreatitis as compared to those with nonpainful CP." (PMID 39674387, 2025).
coronary artery stenosis (4 papers, 2020 to 2022). "The correlation analysis of SAH, IL-1β, Hcy, TNF-α, BDNF and the number of coronary artery stenosis was conducted by Kendall’s tau-b correlation, respectively." (PMID 35282820, 2022). "SAH, IL-1β, Hcy, TNF-α and BDNF in serum of patients with CHD can be used as effective biological indicators to monitor the degree of CHD and severity of coronary stenosis." (PMID 35282820, 2022).
erectile dysfunction (4 papers, 2022 to 2025). Persistent or recurrent inability to achieve or to maintain an erection during sexual activity. "Similarly, in the emerging field of erectile dysfunction research, low-intensity ESWT had been shown to enhance nerve regeneration and functional recovery by upregulating BDNF expression." (PMID 39650239, 2024).
essential hypertension (4 papers, 2016 to 2023). Hypertension that presents without an identifiable cause. "BDNF Val66Met modulates hypothalamic-pituitary-adrenal axis reactivity and regulation, with women bearing Val/Met genotype and men bearing Val/Val being particularly vulnerable to psychological stress, an essential etiology for primary hypertension." (PMID 28056856, 2017).
functional dyspepsia (4 papers, 2019 to 2023). "Fourteen genes corresponding to two gene sets were identified, and the functional dyspepsia-related genes targeted by the activated F. fructus compound were ADRA2A, BDNF, CCK, CRP, GCG, JUN, Kcnh2, PTGS1, PTGS2, Pyy, SLC6A4, and TRPV." (PMID 37375548, 2023). "Since increased CRF and decreased BDNF have been observed in increased anxiety- and depressive-like behavior, the altered gene expression may contribute to the central mechanisms responsible for vagal afferent induced psychological disorders in functional dyspepsia." (PMID 35527812, 2022). "Furthermore, in a rat model of functional dyspepsia vagal afferent hypersensitivity was accompanied by an increase and decrease in gene expression of CRF and BDNF respectively in the amygdala, with the altered expression partially normalized by subdiaphragmatic vagotomy." (PMID 35527812, 2022).
generalized epilepsy (4 papers, 2020 to 2024). Epilepsy that is characterized by generalized seizure types and may have typical interictal and/or ictal EEG findings that accompany generalized seizure types (for example generalized spike-wave). "For cg13974632 (BDNF), there was some evidence for a positive association of genetic generalized epilepsy with increased DNA methylation using the weighted median method." (PMID 31915053, 2020). "Furthermore, continuous administration of BDNF by a bio-delivery system attenuates generalized epilepsy in rats." (PMID 38006577, 2024).
Hepatic fibrosis (4 papers, 2020 to 2025). The presence of excessive fibrous connective tissue in the liver. "This is the first study showing the associations of serum BDNF levels with liver enzymes and hepatic fibrosis-related indices, which may underlie liver-brain interactions." (PMID 35998179, 2022). "In conclusion, our results demonstrate associations of serum BDNF levels with liver enzymes and hepatic fibrosis-related indices, which may underlie liver-brain interactions." (PMID 35998179, 2022). "In PBC patients, higher BDNF levels correlated inversely with liver stiffness measured by ElastPQ (R = −0.39, p = 0.0258), spleen dimensions, splenic vein flow volume (R = −0.49, p = 0.0018), suggesting an association with milder liver fibrosis and early hemodynamic alterations." (PMID 40806277, 2025). "Thus, BDNF may be responsible for the association of altered hepatic enzymes and hepatic fibrosis-related indices with brain function and health." (PMID 35998179, 2022). "Experimental models demonstrated increased BDNF expression in fibrotic liver tissue from patients with chronic hepatitis B and in animal models of liver fibrosis." (PMID 40806277, 2025). "Based on these observations, we hypothesized that circulating BDNF levels are altered in patients with PBC and associated with key clinical features, including liver fibrosis, liver biochemistry, minimal hepatic encephalopathy, and fatigue severity." (PMID 40806277, 2025). "To test this hypothesis, we investigated the correlation of serum BDNF concentration with the activity of hepatic enzymes and hepatic fibrosis-related indices in healthy middle-aged and older females." (PMID 35998179, 2022). "However, our findings raise the possibility that circulating BDNF may serve as a non-invasive biomarker for milder liver fibrosis in early-stage PBC." (PMID 40806277, 2025). "The role of CNTF and BDNF in hepatic fibrosis is not understood." (PMID 32175323, 2020).
infectious colitis (4 papers, 2021 to 2025). A viral or bacterial infectious process affecting the large intestine. "For example, a study found that Bifidobacterium longum NCC3001 normalizes anxiety-like behavior and hippocampal brain-derived neurotrophic factor (BDNF) in mice with infectious colitis." (PMID 40703243, 2025).
lymphopenia (4 papers, 2016 to 2023). Reduction in the number of lymphocytes. "While trends towards lower levels on parameters of muscle damage were observed, Tr14 affected lymphopenia, cellular and soluble activation markers, lowered exercise-induced neutrocytosis, and reduced the expression of selected growth factors such as BDNF." (PMID 27478305, 2016). "Here, we demonstrate that O3-induced increases in circulating corticosterone and lymphopenia were not influenced by preexistent CS or SI; however, circulating BDNF was depleted in both stress conditions regardless of O3 exposure." (PMID 38001817, 2023).
motor neuron disease (4 papers, 2010 to 2023). "Mouse model of motor neuron disease (SOD1-G93A) was injected intramuscularly with Brain-derived neurotrophic factor (BDNF-TTC) encoding or control naked DNA plasmids." (PMID 21044297, 2010). "The initial findings that BDNF rescues injury-induced motor neurons death and motor dysfunction in the wobbler mouse model of motor neuron disease provided the rationale for the clinical use of BDNF in ALS patients." (PMID 35321093, 2022). "In animal models of motor neuron disease, brain-derived neurotrophic factor (BDNF) and neurotrophin-3 (NT-3) decreased MNs degeneration and contributed to increased lifespan of the studied animal group." (PMID 32041109, 2020). "Exogenous treatment with CNTF dramatically reduces degeneration in progressive motor neuropathy mice and co-treatment of the wobbler mouse model of motor neuron disease with CNTF and BDNF completely arrests disease progression for 1 month." (PMID 37692101, 2023).
Myocardial fibrosis (4 papers, 2017 to 2025). "The authors also noted evidence of elevated myocardial fibrosis and apoptosis and attribute the changes to the synergistic depletion of brain‐derived neurotrophic factor signaling." (PMID 35076176, 2022). "Immunohistochemical staining indicated accelerated myocardial fibrosis in response to sh-BDNF and K252a in the presence of sh-G9a." (PMID 35439934, 2022).
myopia (4 papers, 2007 to 2026). "Furthermore, the imbalance between oxidative stress, NGF, and BDNF in human high myopia, which showed an association with total nitrite levels, was also observed." (PMID 40650128, 2025). "Herein, we report the differential expression of NGF, BDNF, and related receptors between myopia and high myopia, and their association with NO/nitrites/iNOS/NOX1/4, KEAP1/NRF2, and some epigenetic factors (HDMT3α, HD1), as observed from studies on aqueous and myopic LEC." (PMID 40650128, 2025). "While the exact role of BDNF in myopia has not been clearly identified to date, lower levels of BDNF have been found in the aqueous humor of myopic individuals, and polymorphisms in the noncoding RNA gene BDNF-AS, the antisense RNA of BDNF, have been associated with myopia." (PMID 39876870, 2024). "Herein, we prospect the contribution of NGF and BDNF, throughout transcript and receptors modulation, in myopia and high myopia, prospecting their involvement at both inflammatory and neuroprotective levels." (PMID 40650128, 2025). "SNPs were also analyzed in genes where their expression pattern or their association with syndromes conveys myopia as part of the phenotype (FGF2, BDNF, COL2A1, COL18A1, and PAX6)." (PMID 17653045, 2007). "As deprivation is a major paradigm for producing experimental myopia, brain-derived neurotrophic factor (BDNF) is of interest as a potential genetic marker for myopia." (PMID 17653045, 2007). "Others were chosen for their potential biological relevance to myopia (FGF2, BDNF, and PAX6)." (PMID 17653045, 2007). "Some studies focused on the role of TGF-β in myopia development, being a key regulator of scleral remodeling, which can contribute to eye elongation and myopia progression, prospecting the hypothesis that NGF and BDNF might also act as additional remodeling factors." (PMID 40650128, 2025).
normal tension glaucoma (4 papers, 2016 to 2024). "Ghaffariyeh and co-workers reported a reduction of BDNF tear levels in normal tension glaucoma patients and a significant reduction of BDNF serum levels in early glaucoma." (PMID 28068360, 2017).
pancreatic ductal adenocarcinoma (4 papers, 2016 to 2024). An infiltrating adenocarcinoma that arises from the epithelial cells of the pancreas. "Renz et al29 uncovered a relationship between the expression of brain‐derived neurotrophic factor, nerve density, and increased survival of patients on nonselective β‐blockers in the cohort of patients with pancreatic ductal adenocarcinoma." (PMID 39673324, 2024).
parasitemia (4 papers, 2020 to 2025). "The BDNF concentrations were significantly lower (p<0.01) in children with RAP compared to children with subclinical parasitic infections." (PMID 34539633, 2021). "The BDNF, cytokines and kynurenine profiles in children with RAP and children with subclinical parasitic infections." (PMID 34539633, 2021). "BDNF levels were significantly increased in the Toxo-BRB and Ket-BRB groups from those in the Toxo-SAL and Ket-SAL groups (P = 0.01), indicating protective effects of BRB on memory reconsolidation induced by parasite infection and Ket." (PMID 37649038, 2023).